HAND2 (heart and neural crest derivatives expressed 2)
Diseases named in the same sentence as HAND2 in open-access papers (continued):
Sharing a sentence is not in itself a finding about the gene and the disease.
heart failure (6 papers, 2011 to 2024). Inability of the heart to pump blood at an adequate rate to meet tissue metabolic requirements. "Thus, modulation of miR‐122 and Hand2 could potentially be therapeutically useful against heart failure or other diseases where miR‐122 plays a causal role." (PMID 33942477, 2021). "Mechanistically, miR-122 promotes apoptosis by inhibiting the Hand2 transcription factor, which increases Drp1-mediated mitochondrial fission, potentially contributing to heart failure." (PMID 39857629, 2024). "Hand2 expression was inhibited by blocking Uph transcription, resulting in ventricular hypoplasia, outflow defects, and heart failure, leading to embryonic death, similar to the effects of transgenic Hand2 deletion in embryos." (PMID 37759546, 2023). "Cardiac-specific overexpression of miR-122, elevated in heart failure patients, induces mitochondria-dependent cardiomyocyte apoptosis and accelerates heart failure through the activation of Drp1 by inhibiting Hand2." (PMID 37895224, 2023). "Targeted gene deletion of HAND2 in mouse embryos resulted in embryonic lethality from heart failure." (PMID 22136190, 2011). "Our work here is the first to implicate Hand2 in rodent phenotypes resembling heart failure." (PMID 33942477, 2021).
cardiac hypertrophy (4 papers, 2020 to 2022). "The Hand2 transcription factor normally plays an essential role in cardiac morphogenesis, with disruption or loss of Hand2 causing impaired cardiac development, apoptosis of cardiomyocytes and cardiac hypertrophy." (PMID 33942477, 2021). "Next, Hand2 transcription factor normally plays an essential role in cardiac morphogenesis and its disruption can cause impaired cardiac development, apoptosis of cardiomyocytes, and cardiac hypertrophy." (PMID 36499336, 2022). "Conversely, these latter genes together with GATA4 and HAND2 resulted upregulated in V samples, belonging to functional categories of heart development and cardiac hypertrophy." (PMID 31975556, 2020). "Note that no heart hypertrophy was detected, which suggests that Hand2 expression in more cephalic levels of the sympathetic ganglion chain is less compromised than in the caudal regions innervating hindlimb muscles." (PMID 33258279, 2021).
endometriosis (4 papers, 2016 to 2025). The growth of functional endometrial tissue in anatomic sites outside the uterine body. "Both Org OD 02-0 concentrations mimicked the effects of P4 by upregulating the expression of IGFBP1, PRL, HAND2, and ZBTB16 in control, eutopic, and ectopic cells from women with endometriosis, suggesting the involvement of mPRs in the decidualization process of endometrial cells." (PMID 40806428, 2025). "HAND2 expression was detected in THESC cells (positive control), ESCs from women without endometriosis and in eutopic and ectopic ESCs from endometriosis patients." (PMID 40806428, 2025).
Tetralogy of Fallot (4 papers, 2014 to 2017). A congenital cardiac malformation comprising pulmonary stenosis, overriding aorta, ventricular septum defect, and right ventricular hypertrophy. "In humans, HAND2 was strongly expressed in the heart, and patients with genomic deletions or duplications that involved chromosome 4q33, the locus of HAND2, were susceptible to CHD, including VSD, tetralogy of Fallot (TOF), pulmonary atresia, and coarctation of the aorta." (PMID 26865696, 2016).
tricuspid atresia (4 papers, 2012 to 2025). Tricuspid atresia is (TA) a rare congenital heart malformation characterized by the congenital agenesis of tricuspid valve leading to severe hypoplasia of right ventricle (functionally univentricular). "In fact, the functional synergy between both proteins was reduced by 50% over the DEGS1 promoter, which was recently shown by our group to be directly regulated by NFAT and HAND2 in chronic hypoxia, a mouse model mimicking cyanotic CHD including Tricuspid Atresia (unpublished data)." (PMID 23226213, 2012).
ventricular septal defect (4 papers, 2016 to 2021). The presence of a defect (opening) in the septum that separates the two ventricles of the heart. "HAND2 loss-of-function mutation was found to contribute to human CHDs, and enhanced susceptibility to familial ventricular septal defect (VSD) and double outlet right ventricle (DORV)." (PMID 34576009, 2021). "The miR-1-2 overexpression or Hand2 targeted knockout resulted in a similar embryonic lethality phenotype in mice, while miR-1-2 deletion led to a fourfold increase in Hand2 protein levels and homozygous lethality due to ventricular septal defects (VSD)." (PMID 31752983, 2019).
atrial fibrillation (3 papers, 2017 to 2025). A disorder characterized by an electrocardiographic finding of a supraventricular arrhythmia characterized by the replacement of consistent P waves by rapid oscillations or fibrillatory waves that vary in size, shape and timing and are accompanied by an irregular ventricular response. "Similarly, variants near GATA4 and members of the HOXB family of transcription factors such as HOXB7 have been associated with hypertension, while HAND2 variants are associated with aortic dimension and atrial fibrillation." (PMID 40931195, 2025). "This extended gene network contained a number of transcription factors (Tbx5, Hand2, Fhl2, and Gata4) and ion/calcium handling genes (Ank2, Cacna2d2, Scn5a, Kcnd2, Kcnj5, Myoz2, Casq2, Csrp3, and Gja3) of interest in the context of atrial fibrillation." (PMID 28720711, 2017). "At the RNA level, RT-qPCR confirmed expression changes in CACNG4 (cardiac arrythmia), GJA5 (atrial fibrillation), THBS2 (angiogenesis inhibitor), ADD2 (membrane skeletal protein, synaptic plasticity), and HAND2 (neurogenesis)." (PMID 39508990, 2025).
liver fibrosis (3 papers, 2018 to 2025). "We found that 0.06% TAA treatment induced liver fibrosis, characterised by increased RNA expression of collagen, Hand-2 and Acta-2, smaller liver sizes and collagen deposition." (PMID 30375438, 2018).
lung adenocarcinoma (3 papers, 2017 to 2021). A carcinoma that arises from the lung and is characterized by the presence of malignant glandular epithelial cells. "HAND2 was found either hypermethylated or hypomethylated in different stages of lung adenocarcinoma." (PMID 34262872, 2021). "HAND2, as the transcript factor, is over-expressed in early stage of lung squamous cell carcinoma instead of lung adenocarcinoma." (PMID 28350845, 2017).
lung squamous cell carcinoma (3 papers, 2017 to 2020). "In contrast, another recent study showed that HAND2 was hypermethylated and downregulated in colon cancer, while another study demonstrated that HAND2 was overexpressed in the lung squamous cell carcinoma." (PMID 33273919, 2020). "There are some studies that have demonstrated HAND2 over-expression in the lung squamous cell carcinomas and de-regulated in the histological subtypes." (PMID 28959347, 2017).
Obesity (3 papers, 2019 to 2025). Accumulation of substantial excess body fat. "In summary, our study identifies HAND2 as a novel obesity-linked adipocyte transcription factor, highlighting new mechanisms of GR-dependent adipogenesis in humans and mice." (PMID 34014371, 2021). "We found that HAND2 is an obesity-linked white adipocyte transcription factor regulated by glucocorticoids that was necessary but insufficient for adipocyte differentiation in vitro." (PMID 34014371, 2021). "In this study, we show that HAND2 is a critical factor for early adipogenesis, regulated by GC–GR signalling and correlated to body weight and obesity in mice and humans." (PMID 34014371, 2021). "In summary, our study introduces HAND2 as a novel player in adipogenesis and highlights a new layer of GC–GR signalling, thus enhancing our understanding of adipocyte biology in obesity." (PMID 34014371, 2021). "Under these conditions, reactivation of HAND2 expression in obesity could help stimulate adipogenesis and healthy adipose tissue expansion, thus restoring insulin sensitivity and metabolic health." (PMID 34014371, 2021). "Moreover, gWAT Hand2 was significantly lower in mouse models of obesity, including HFD-induced obesity (referred to here as diet-induced obesity [DIO]) as well as genetically obese, leptin receptor-deficient db/db mice, and also inversely correlated with body weight." (PMID 34014371, 2021). "Methylation of several gene promoters, such as HAND2, HOXC6, and PPARG, influences adipogenesis and differentiation, obesity, lipid metabolism, and adipose tissue expandability." (PMID 30911298, 2019).
adenomyosis (2 papers, 2023 to 2025). The growth of endometrial tissue inside the muscular wall of the uterine corpus. "Subsequent analysis revealed a distinct decrease in the expression of decidualization marker HAND2 and endometrial receptivity marker LIF in the adenomyosis model." (PMID 39794729, 2025).
cardiomyopathies (2 papers, 2011 to 2024). "Hand1 and Hand2 were found involved in the development of cardiomyopathy in rodents and human." (PMID 21559426, 2011). "We identified further genes that regulate the development of trabeculation (NKX2-5, TBX20, HAND2, NRG1, NOTCH1 and DTNA) and those with evidence of involvement in cardiomyopathies (CRYAB and RIT1 (ARHGEF2))." (PMID 39567769, 2024).
colon carcinoma (2 papers, 2020 to 2022). "In the present study, HAND2 was identified as a monotonically decreasing gene in colon cancer while a monotonically increasing gene in NSCLC, which is basically consistent with the results of the two previous studies." (PMID 33273919, 2020). "It is observed that one overlap, i.e., COMMD7 (COMM domain containing 7) existed in the MEGs for colon and esophageal cancer, whereas the other overlap, i.e., HAND2 (heart and neural crest derivatives Expressing 2) existed in the MEGs for colon cancer and NSCLC." (PMID 33273919, 2020). "Interestingly, the aggregated (mean of all probes) Pearson's correlation (Pearson's correlation coefficient = -0.44, p = 6.6e-14 for COAD) conveyed that HAND2 significantly downregulated in CRC (288 colon cancer) and has a reverse correlation with the methylation status of CpG islands." (PMID 36443682, 2022).
colorectal cancer (2 papers, 2022). A primary or metastatic malignant neoplasm that affects the colon or rectum. "Also, the data obtained from the DepMap database shows a significant negative correlation (Pearson's Correlation Coefficient = -0.3035, p = 0.030) between the HAND2 methylation and expression in colorectal cancer cell line data." (PMID 36443682, 2022).
endometrioid adenocarcinoma (2 papers, 2017 to 2022). An adenocarcinoma characterized by the presence of malignant glandular epithelial cells resembling endometrial cells. "However, in our CAFs model, despite an increased in IRS2 expression, there is a decreased in HAND2 expression, parallel to previously reported study which demonstrated loss of HAND2 expression in the stromal of atypical hyperplasia and endometrioid adenocarcinomas compared to normal fibroblasts." (PMID 35816477, 2022). "HAND2 is absent in endometrioid carcinoma and reduced in atypical hyperplasia compared to benign endometrium; knockout of HAND2 leads to continuous proliferation in mice model." (PMID 28350845, 2017).
hepatocellular carcinoma (2 papers, 2019 to 2022). A malignant tumor that arises from hepatocytes. "They reported that HAND2- AS1 is downregulated in common tumors such as hepatocellular carcinoma (HCC) and colorectal cancer (CRC)." (PMID 35525925, 2022).
mesothelioma (2 papers, 2022). A usually malignant and aggressive neoplasm of the mesothelium which is often associated with exposure to asbestos. "HAND2 expression coincided with differential expression of the previously mesothelium- and mesothelioma-associated genes MSLN and WT1, as well as with GATA5 and MEIS2." (PMID 35354817, 2022). "We compared gene expression for HAND2 and other mesothelial progenitor genes with a collection of mesothelioma-associated genes, and several tissue-specific and ubiquitous house-keeping genes." (PMID 35354817, 2022). "expressed that loss of HAND2 disrupted mesothelium formation with reduced progenitor cells and perturbed migration, which leads to mesothelioma tumor formation." (PMID 36443682, 2022). "Our findings propose that Hand2 expression contributes to the unique properties of mesothelial progenitor cells in development and in mesothelioma." (PMID 35354817, 2022). "In mouse and human mesothelioma, we document expression of LPM-associated transcription factors including Hand2, suggesting re-initiation of a developmental program." (PMID 35354817, 2022). "This HAND2-expressing group of mesothelioma tumors did not cluster notably with tumors featuring differential expression of the common mesothelioma-associated tumor suppressor genes BAP1 and CDKN2A." (PMID 35354817, 2022). "We next sought to corroborate whether human mesothelioma also feature HAND2 expression." (PMID 35354817, 2022). "We link the developmental function of Hand2 in mesothelium formation to a reactivation of an early coelomic epithelium-focused LPM program in mouse and human mesothelioma tumors." (PMID 35354817, 2022).
myocardial infarcts (2 papers, 2013 to 2017). "Of particular interest, the recommendation to screen for HAND2 and TBX5 variants in families at risk for early and fatal myocardial infarcts." (PMID 28469241, 2017). "Two recent reports demonstrated that following myocardial infarction delivery of Gata4, Mef2c, and Tbx5, or GATA4, HAND2, MEF2C, and TBX5 in the injured myocardium successfully reprogrammed cardiac fibroblasts into cardiomyocytes." (PMID 23704920, 2013).
Saethre-Chotzen syndrome (2 papers, 2017 to 2023). Saethre-Chotzen syndrome (SCS) is an inherited craniosynostosis syndrome characterized by unilateral or bilateral coronal synostosis, facial asymmetry, ptosis, strabismus and small ears with prominent crus, among other less common manifestations. "Direct interactions of HAND2 with TWIST1 are essential for limb bud development, as their altered dimerization causes Saethre-Chotzen syndrome with associated distal limb skeletal malformations." (PMID 37414772, 2023).
Arrhythmia (1 paper, 2022). Any cardiac rhythm other than the normal sinus rhythm. "Overall, our findings indicate that embryonic loss of cardiac Hand2 expression predisposes to arrhythmias and causes abnormal conduction across the CCS." (PMID 35877576, 2022). "Notably; however, some adult H2LVCreCKO mice have varying P-wave morphology and atrial tachycardia, suggesting that embryonic loss of cardiac Hand2 expression alters atrial electrical properties, increasing their arrhythmia susceptibility." (PMID 35877576, 2022).
atherosclerosis (1 paper, 2024). A disease characterized by the build-up of fatty material and calcium deposition in the arterial wall resulting in partial or complete occlusion of the arterial lumen. "The extremely strong CIMT association from our inferred gene expression networks under the regulation of genetically polymorphic ZNF385D and HAND2 is in support of genetically controlled functional pathways independent of lifestyle and behavior factors in the development of atherosclerosis." (PMID 38397203, 2024).
autism (1 paper, 2018). Persistent deficits in social interaction and communication and interaction as well as a markedly restricted repertoire of activity and interest as well as repetitive patterns of behavior. "Here, we show significant downregulation of the transcription factors FOXO1 and HAND2 in neurons from 15q duplication, but not AS deletion subjects suggesting that disruptions in transcriptional regulation may be a driving factor in the autism phenotype in Dup15q syndrome." (PMID 29423132, 2018).
brain tumor (1 paper, 2025). "Conversely, NB-FOXR2 lacked expression of the characteristic TFs and marker genes of EC-NB, except for ASCL1, known for its essential role in multiple CNS neural lineages and expressed across brain tumor types, and, to a lower level, HAND2." (PMID 39495206, 2025).
Corneal opacity (1 paper, 2025). A reduction of corneal clarity. "Among KC-specific TFs, Hand2 and Tbx1 are the major transcription factors that regulate vascularization, which is the main cause of corneal opacity." (PMID 39896421, 2025).
coronary artery disease (1 paper, 2017). "We documented a novel interaction between TBX5 and HAND2, and showed that a p.G202V HAND2 variant associated with CHD and coronary artery diseases found in a large Lebanese family with high consanguinity, drastically inhibited this interaction by 90%." (PMID 28469241, 2017). "In contrast, and of particular interest is the coronary artery disease problem which could be explained by the defective interaction of the p.G202V HAND2 protein with TBX5." (PMID 28469241, 2017).
endometrial tumor (1 paper, 2020). "Notably, our previous and present studies revealed that HAND2 was less expressed in the ER-α positive endometrial tumor tissues compared with the normal endometrial tissues." (PMID 33511117, 2020).
epithelioid mesothelioma (1 paper, 2022). "We further detected nuclear HAND2 immunoreactivity in an epithelioid mesothelioma sample with high HAND2 mRNA levels." (PMID 35354817, 2022).
female infertility (1 paper, 2021). Diminished or absent ability of a female to achieve conception. "It modulates stromal–epithelial communications through negative regulation of FGF signaling and genetic ablation of Hand2 in the mouse lead to female infertility largely due to decidualization failure." (PMID 34292881, 2021).
hypothyroidism (1 paper, 2025). Abnormally low levels of thyroid hormone. "Additionally, hypothyroidism led to reduced uterine gene expression of LIF, BMP2, WNT4, and HAND2." (PMID 39859259, 2025).
Infertility (1 paper, 2025). "Given the potential indirect influence of male-factor infertility on endometrial receptivity, we additionally examined the expression of key endometrial functional markers—FOXO1, HAND2, HOXA10, and KI67—in both groups." (PMID 41199770, 2025).
keloid (1 paper, 2022). An irregularly shaped, elevated mark on the skin caused by deposits of excessive amounts of collagen during wound healing. "In terms of expression level, BMP4, MSX1, TBX2, SIX1, DLX5, and DLX2 were lowly expressed, while HAND2, IRX1, EDN1, and MEF2C were highly expressed in keloid fibroblasts." (PMID 35047146, 2022).
lung carcinoma (1 paper, 2017). "Although HAND2 did not display an obvious up- or down-regulation in the lung carcinoma cell at three-time points, the trend of up-regulation seems obvious (log2ratio>0)." (PMID 28959347, 2017).
omphalocele (1 paper, 2025). Omphalocele is an embryopathy classified in the group of abdominal celosomias and is characterized by a large hernia of the abdominal wall, centered on the umbilical cord, in which the protruding viscera are protected by a sac. "RNA-seq analysis reveals that most of the altered gene expression observed in Hand1 mutants is restored; however, the majority of Hand1Hand2/Hand2 progeny die as neonates with omphalocele, suggesting that HAND2 cannot fully rescue HAND1 function within ventral body wall, dm and umbilical tissues." (PMID 40960281, 2025). "To understand where the Hand1 expression domain could be contributing to omphalocele in the Hand1Hand2/Hand2 embryos beyond expression within the dorsal mesentery and gut, we interrogated Hand1 expression using our Hand1lacZ/+ allele at E11.5." (PMID 40960281, 2025). "Importantly, no Hand1ΔLV/Hand2 mice presented with omphalocele." (PMID 40960281, 2025).
ovarian carcinoma (1 paper, 2020). A malignant neoplasm originating from the surface ovarian epithelium. "However, only AOX1 of top five down-regulated genes was verified to be decreased in expression for expanding sample of ovarian cancers, with that of REEP1, BNC1, HAND2, and GSDME unchanged." (PMID 33135729, 2020).